GPC6 (glypican 6)
Diseases named in the same sentence as GPC6 in open-access papers (continued):
Sharing a sentence is not in itself a finding about the gene and the disease.
melanoma (5 papers, 2019 to 2022). A malignant, usually aggressive tumor composed of atypical, neoplastic melanocytes. "Just as FN1, glypican-6 is upregulated in melanoma cells versus melanocytes and in metastatic versus primary melanoma." (PMID 33870460, 2021). "Glypican 6 is used to distinguish between the primary tumors of melanoma and regional cutaneous/subcutaneous metastases during early metastasis." (PMID 33336008, 2020). "In this report, we used both computational and experimental approaches to try to understand the role of GPC6 in the progression of melanoma." (PMID 31199813, 2019). "Spearman correlation coefficients between GPC6 and the top 10 positively and 5 negatively correlated genes in melanoma RNA-seq samples." (PMID 31199813, 2019). "We overexpressed miR-509-3p in A375 melanoma cells and showed that GPC6 expression was significantly suppressed." (PMID 31199813, 2019). "Using RNA-seq gene expression data from TCGA, we identified GPC6 among a set of genes whose expression levels can distinguish primary skin melanoma from melanoma metastasized to cutaneous/subcutaneous tissue." (PMID 31199813, 2019). "In TCGA melanoma samples, we also showed that GPC6 expression was negatively correlated with miR-509-3p, which has previously been shown to function as a tumor suppressor in various cancer cell lines." (PMID 31199813, 2019). "Among the top ten genes whose expression levels distinguish primary from metastatic melanoma, we focused our subsequent analyses on a putative novel biomaker, GPC6, whose expression level was up-regulated in metastatic melanoma compared to primary melanoma." (PMID 31199813, 2019). "In melanomas, genes coordinately expressed with GPC6 were largely those involved in cell adhesion and migration including INHBA, PDGFC, PDGFRA, PPAP2B, SPRX2, TCF4, and TNFAIP6 and ZEB1." (PMID 31199813, 2019). "miR-509-1 expression was negatively correlated with that of GPC6 in TCGA melanoma samples (r = -0.41, Spearman correlation)." (PMID 31199813, 2019). "We showed that overexpression of miR-509-3p mimic in A375 melanoma cells suppressed GPC6 expression." (PMID 31199813, 2019). "GPC6 was among a group of genes whose expression levels were significantly correlated with reduced time of disease-free status in melanoma." (PMID 31199813, 2019). "ZEB1 exhibited the highest correlation with that of GPC6 (r = 0.63, Spearman correlation) when all 389 melanoma samples were combined." (PMID 31199813, 2019). "GPC6 expression was positively correlated with expression of many genes that are involved in cell adhesion and migration in melanoma samples as well as in samples from other tumors from TCGA." (PMID 31199813, 2019). "Together, our findings identified GPC6 as an early biomarker for melanoma metastatic progression, one that can be regulated by miR-509-3p." (PMID 31199813, 2019). "We showed that GPC6 expression was up-regulated in a melanoma cell line compared to normal melanocytes and in metastatic melanoma compared to primary melanoma." (PMID 31199813, 2019). "Glypican-6 is recently proposed as a new putative biomarker of progression in melanoma." (PMID 33870460, 2021). "Similarly, GPC6 was identified as a putative biomarker for the metastatic progression of cutaneous melanoma, since it is possible to track higher levels of GPC6 in melanoma samples when compared with normal melanocytes." (PMID 33494442, 2021). "Glypican 6 expression is higher in metastatic melanoma than in primary melanoma and is higher in primary melanoma than in normal melanocytes; therefore, this gene may be a biomarker for the metastatic progression of melanoma." (PMID 33336008, 2020). "In this report, we focused on a new putative melanoma gene, glypican 6 (GPC6)." (PMID 31199813, 2019). "GPC6 was up-regulated in a melanoma cell line compared to normal melanocytes." (PMID 31199813, 2019).
melanoma (continued). "We identified two putative miR-509-3p binding sites in the 3’-UTR of human GPC6 gene and hypothesized that GPC6 is a putative target of miR-509-3a in melanoma cells." (PMID 31199813, 2019). "Next, we investigated a possible mechanism for GPC6 overexpression in melanoma." (PMID 31199813, 2019). "Furthermore, GPC6 expression was positively correlated with genes largely involved in cell adhesion and migration in both melanoma samples and in RNA-seq samples from other TCGA tumors." (PMID 31199813, 2019). "Although little is known about the role of GPC6 in tumor progression and metastasis in melanoma and other tumors, one would speculate that GPC6 functions also through Wnt, FGF, Hedgehog, and BMP signaling." (PMID 31199813, 2019). "Analysis of all 389 melanoma samples revealed 82 genes whose expression levels were strongly positively correlated (r ≥ 0.5, Spearman correlation), and seven that were strongly negatively correlated (r ≤ -0.5, Spearman correlation) with GPC6." (PMID 31199813, 2019). "By comparing the gene expression data from primary and cutaneous melanoma samples from The Cancer Genome Atlas (TCGA), we identified GPC6 among a set of genes whose expression levels can distinguish between primary melanoma and regional cutaneous/subcutaneous metastases." (PMID 31199813, 2019). "Using public array gene expression data from the Encyclopedia of DNA Elements (ENCODE), we found that GPC6 was also up-regulated in a melanoma cell line (mel_2183) compared to normal melanocytes (GSE15805) and is overexpressed in metastatic melanoma compared to primary melanoma." (PMID 31199813, 2019). "The correlation in expression between GPC6 and ZEB1 is evident within each of the four categories of melanoma." (PMID 31199813, 2019). "GPC6 expression was elevated in melanoma samples compared to normal melanocytes and elevated in melanomas that had metastasized to regional cutaneous/subcutaneous tissue, lymph node, or distant organs compared to primary melanomas." (PMID 31199813, 2019).
autism (3 papers, 2011 to 2021). Persistent deficits in social interaction and communication and interaction as well as a markedly restricted repertoire of activity and interest as well as repetitive patterns of behavior. "For instance, in a genome-wide study in autism patients to identify novel copy number variations (CNVs), four independent CNVs in the GPC5/GPC6 gene cluster were identified." (PMID 29434536, 2018).
multiple sclerosis (3 papers, 2011 to 2021). A progressive autoimmune disorder affecting the central nervous system resulting in demyelination. "Lastly, in the last year, genome wide association studies have identified GPC6 as a risk factor multiple sclerosis and for Alzheimer’s in African Americans further suggesting a role for GPC6 in maintaining neuronal function." (PMID 33762006, 2021). "The chromosomal region of 13q31-32, where GPC5 and GPC6 are located, has been previously identified in a GWAS as showing a significant association with genetic susceptibility of multiple sclerosis (MS)." (PMID 32398079, 2020). "Both GPC6 (glypican 6) and CLEC16A (C-type lectin domain family 16, member A) are associated with multiple sclerosis." (PMID 21886828, 2011).
osteoporosis (3 papers, 2019 to 2025). A condition of reduced bone mass, with decreased cortical thickness and a decrease in the number and size of the trabeculae of cancellous bone (but normal chemical composition), resulting in increased fracture incidence. "Interestingly, GPC6 seems to increase the risk of spinal osteoarthritis by causing osteoporosis, and osteoarthritis in the spine increases the levels of inflammatory cytokines such as IL‐1, and TNF‐a, which lead to homeostatic imbalance in disk matrix." (PMID 31111662, 2019).
bipolar disorder (2 papers, 2007 to 2011). A disorder of the brain that causes unusual shifts in mood, energy, activity levels and the ability to carry out day-to-day tasks. "For example, 10 genes among the 16 confirmed genes (Cacng2, Dnajc3, Dusp4, Gpc6, Mbp, Nov, Phf21b, Atxn10, Xbp1, and Zfyve28) have their human orthologs located within a 10 Mb region flanking the linkage markers for bipolar disorder, and thus merit further study." (PMID 18028544, 2007).
colon cancer (2 papers, 2024 to 2025). "The hypermethylation and down-regulated mRNA expression of the GPC6 have consistently been observed in colon cancer, as reported in a previous study." (PMID 39030645, 2024). "We found targets not previously studied in STS like GPC6, a member of the glypican family which is pathogenic in sarcomas, or CLMP, described as tumor suppressor in colon cancer." (PMID 40814001, 2025).
glioma (2 papers, 2016 to 2024). A benign or malignant brain and spinal cord tumor that arises from glial cells (astrocytes, oligodendrocytes, ependymal cells). "Utilizing established, publicly available datasets, we observed that GPC6 expression is significantly increased in both low-grade glioma (LGG) and GBM compared to normal brain tissue." (PMID 38802334, 2024). "Lastly, to validate the presence of GPC6 in human patients, we tested for GPC6 protein in a glioma tissue microarray, finding enhanced expression in tumor samples compared to normal brain." (PMID 38802334, 2024). "To test for this, we overexpressed GPC6 in our IUE mouse glioma model." (PMID 38802334, 2024).
lumbar disk herniation (2 papers, 2019 to 2025). "In conclusion, this study reported the potential association of GPC6 polymorphisms with lumbar disk herniation risk in the Han Chinese population for the first time." (PMID 31111662, 2019). "GPC6 polymorphisms are also associated with lumbar disk herniation." (PMID 41376803, 2025).
metastatic melanoma (2 papers, 2019 to 2020). A melanoma that has spread from its primary site to another anatomic site. "GPC6 expression was up-regulated in TCGA metastatic melanoma samples compared to normal samples, however, its expression levels showed a metastasis stage-dependent decrease with an overall lowest expression in tumors metastasized to distant organs." (PMID 31199813, 2019).
nasopharyngeal carcinoma (2 papers, 2021 to 2022). A carcinoma arising from the nasopharyngeal epithelium. "Fan Cet al. have demonstrated that GPC-6 promotes proliferation, migration, and invasion of tumor cells in nasopharyngeal carcinoma." (PMID 33902495, 2021).
neuroblastoma (2 papers, 2018 to 2021). Neuroblastoma (NB) is the most common solid, extracranial childhood tumor. "This study also found that high GDE2 or low GPC6 level in neuroblastoma predicted significantly increased patient survival." (PMID 30197623, 2018). "Overexpression of GDE2/GDPD5 in neuroblastoma and SH-SY5Y neuronal cells facilitates the release of GPC6 and decreases the surface level of GPC6." (PMID 34301723, 2021). "Similarly, another study has shown that neuroblastoma differentiation is promoted by release of a GPI-anchored HSPG, Glypican-6 (GPC6) through via Glycerophosphodiesterase (GDE2)." (PMID 30197623, 2018).
schwannoma (2 papers, 2023 to 2024). A benign, usually encapsulated slow growing tumor composed of Schwann cells. "CEMIP, THSD4, and GPC6 were among the topmost DE genes in the Schwannoma nuclei." (PMID 36865335, 2023).
dementia (1 paper, 2010). Loss of intellectual abilities interfering with an individual's social and occupational functions. "If a locus has pleiotropic effects, affecting both neuroticism and dementia in old age, this could generate an age-dependent response-bias towards protective alleles, leading to a genotype by age interaction such as we observed at GPC6." (PMID 20634892, 2010).
gastric adenocarcinoma (1 paper, 2020). "Glypican 6 is highly expressed in gastric adenocarcinoma and may act as a diagnostic and prognostic marker; however, the functional importance and molecular mechanism of glypican 6 in GC remains unclear." (PMID 32478377, 2020).
ischemia (1 paper, 2021). A hypoperfusion of the BLOOD through an organ or tissue caused by a PATHOLOGIC CONSTRICTION or obstruction of its BLOOD VESSELS, or an absence of BLOOD CIRCULATION. "We detected the STAT3 and Gpc6 genes that are associated with synapse formation in astrocytes after ischemia." (PMID 34122124, 2021).
liver fibrosis (1 paper, 2024). "These genes, including Robo1, Gabrb3, Gpc6, Ephb2 and Dlg2, are usually not expressed in healthy liver, and were reported to be upregulated in metabolic dysfunction-associated steatohepatitis and liver fibrosis." (PMID 39456836, 2024).
medulloblastoma (1 paper, 2026). A malignant, invasive embryonal neoplasm arising from the cerebellum. "In this study, we demonstrate the synchronous expression of GPC6 with GLI family zinc finger 1 (GLI1) in both the developing cerebellum and medulloblastoma." (PMID 41320180, 2026).
metabolic syndrome (1 paper, 2025). A cluster of metabolic risk factors for CARDIOVASCULAR DISEASES and TYPE 2 DIABETES MELLITUS. "Of the 22 female-specific MDD/metabolic syndrome pleiotropic regions, possible causal risk loci mapped to multiple genes (GPC6, SHISA9, RP11-154H12.3, KCNG2, TXNL4A, RBFA and ADNP2)." (PMID 40858613, 2025).
metastatic tumors (1 paper, 2018). "In metastatic tumors, a significant downregulation of GPC6 was also detected, its levels being reduced in 87% of the cases analyzed (p < 0.05), with values being around 26% of those determined in healthy tissues." (PMID 29940912, 2018).
motor neuron degeneration (1 paper, 2017). "We hypothesized that if the production of non-membrane bound Glypican 4 and Glypican 6 via GPI-anchor cleavage was crucial to prevent degeneration, we should see diminished production of these proteins in mouse models that exhibit motor neuron degeneration." (PMID 28103900, 2017).
myelomeningocele (1 paper, 2022). Myelomeningocele is the most severe form of spina bifida. "Array-based comparative genomic hybridization of a cohort of 189 Caucasian and Hispanic cases with non-syndromic lumbo-sacral myelomeningocele identified heterozygous deletions of glypican genes GPC5 and GPC6 as a significant risk factor." (PMID 34842271, 2022).
myocardial infarction (1 paper, 2023). Gross necrosis of the myocardium, as a result of interruption of the blood supply to the area, as in coronary thrombosis. "Another recent study reported that serum GPC-6 levels were significantly increased in patients who developed HF after ST-elevated myocardial infarction." (PMID 37872895, 2023).
primary sclerosing cholangitis (1 paper, 2020). "In addition, the gene region 13q31-32 containing both GPC5 and GPC6 has also previously been associated with the increased risk of primary sclerosing cholangitis (PSC), a chronic liver disease where a strong association has been identified between the SNP GPC6-rs9524260 and disease." (PMID 32398079, 2020).
proteinopathies (1 paper, 2023). "In future studies it will be interesting to see how different mRNA targets, beyond dlp/GPC6 mitigate specific phenotypic aspects of FTD and identify additional targets across the spectrum of TDP-43 proteinopathies." (PMID 37864255, 2023).
rhabdomyosarcoma (1 paper, 2009). A rare aggressive malignant mesenchymal neoplasm arising from skeletal muscle. "Glypican genes (GPC5 and GPC6), belong to a family of heparan sulfate proteoglycans that are constantly expressed and up-regulated in rhabdomyosarcoma with an amplified 13q31q32 region." (PMID 19759907, 2009).
Tetralogy of Fallot (1 paper, 2024). A congenital cardiac malformation comprising pulmonary stenosis, overriding aorta, ventricular septum defect, and right ventricular hypertrophy. "Notably, lack of Shh results in a phenotype resembling Tetralogy of Fallot, consistent with the observed anomalies in Gpc6−/−; and Adamts1−/−; Adamts5X hearts." (PMID 38750698, 2024).
tumor (16 papers, 2007 to 2025). "We observed that adding GPC6 significantly accelerated tumor-associated death with a reduction in median survival of 2 weeks (median survival 3xCR vs GPC6: 97 vs 83 days, respectively)." (PMID 38802334, 2024). "The activity was generally greater in 3xCR brains than in GPC6 when tumor expansion was slow, and when expansion accelerated, GPC6 brains favored higher event rates with lower amplitude, indicating unexpected disturbances in mesoscale activity patterns." (PMID 38802334, 2024). "Lastly, we directly compared the two tumor genotypes within the 3 time bins to quantify differences in their impact on extramarginal neuronal activity parameters during progressive stages of tumor invasion (3xCR vs. GPC6 comparisons)." (PMID 38802334, 2024). "To gain a molecular perspective on the changes GPC6 elicits on a tumor brain, we performed bulk tissue RNA-Sequencing (RNA-Seq) from endpoint 3xCR and GPC6 tumors and identified 1917 differentially expressed genes (p value <0.05)." (PMID 38802334, 2024). "3xCR tumors caused increased neuronal firing compared to GPC6 outside the tumor margin, but neurons inside the GPC6 margin were more active than those outside." (PMID 38802334, 2024). "The amplitudes of isolated 3xCR calcium events were elevated in both slow and fast tumor expansion states compared to GPC6 (+102 and +165%, respectively, p = 0.008 for both comparisons, WR test)." (PMID 38802334, 2024). "GPC6 tumors appeared to expand aggressively at first, but less consistently later, while 3xCR tumor continued to expand at the cortical surface." (PMID 38802334, 2024). "In GPC6 tumor brains, there was a stronger modulation in baseline calcium signal before P70, compared to 3xCR." (PMID 38802334, 2024). "The results of GEPIA analysis showed that expression of GPC1, GPC3, GPC4, and GPC6 was significantly higher in PDAC tumor tissues than in normal tissues (P < 0.05)." (PMID 33302876, 2020). "We also computed the pair-wise correlation in gene expression between GPC6 and all other genes in each of the 32 TCGA tumor types (9,511 samples)." (PMID 31199813, 2019). "Analyzing the mesoscopic calcium activity patterns in both 3xCR and GPC6 animals revealed that multiple activity metrics were significantly shifted during periods of high versus low cortical tumor expansion rates, depending on tumor genotype." (PMID 38802334, 2024). "In addition, quantification of local tumor coverage rates (in μm2/day) as a function of time revealed early elevation of GPC6 tumor expansion, and sustained expansion rates of 3xCR tumors, whereas they were lower at late stages in GPC6 animals." (PMID 38802334, 2024). "Therefore, we used awake two-photon high-resolution calcium imaging to analyze somatic glutamatergic neuronal activity patterns and ensemble metrics at the cellular level in seven 3xCR, six GPC6, and eight non-tumor control animals over time." (PMID 38802334, 2024). "We identified differences in activity patterns between 3xCR and GPC6 animals that depended on whether concurrent local tumor expansion was slow or fast." (PMID 38802334, 2024). "In contrast with the early large dynamic changes in tumor fluorescence in the 3xCR model, the representative GPC6 animal exhibited significantly attenuated variations in tumor infiltration over time (example images calculated from four time points between P62 and 83)." (PMID 38802334, 2024). "The mRNA expression of glypican 6 is higher in GC tumor tissues than in normal tissue." (PMID 32478377, 2020). "Taken together, these results suggest that GPC6 may play a role in and serve as a biomarker for tumor metastatic progression and GPC6 expression may be regulated by miR-509-3p." (PMID 31199813, 2019). "Taken together, these studies demonstrated that GPC6 functions in tumor progression." (PMID 31199813, 2019).